PDK1 (pyruvate dehydrogenase kinase 1)
Diseases named in the same sentence as PDK1 in open-access papers (continued):
Sharing a sentence is not in itself a finding about the gene and the disease.
tumor (continued). "Multiple kinases, such as PDK1 and mTORC2, activate AKT, stimulating cell survival and proliferation and promoting tumor growth." (PMID 39980141, 2025). "Overexpression of PDK1 accelerates tumor growth in several malignancies, with continuing activation of the PI3 K/PDK1/AKT pathway." (PMID 40676293, 2025). "Knockout of IGF1R in tumor cells under hypoxia led to an increas of LDH release and apoptosis rates, and reduced phosphorylation of PDK1 and AKT." (PMID 40290443, 2025). "In some pathophysiological conditions, including tumor progression, SIRT1 seemed to activate protective signaling pathways controlled by AKT (serine/threonine-specific protein kinases) and PDK1 (phosphoinositide-dependent protein kinase 1)." (PMID 40507674, 2025). "Our study demonstrated that reducing SLC7A5 expression significantly decreased HK2, LDHA, Glut1, and PDK1 levels in HGC27R cells, MKN45R cells, and tumor tissues." (PMID 40133832, 2025). "NP-427 therapy improved efficacy by decreasing tumor volume, decreasing PI3K/AKT/PDK1 expression, and boosting tumor necrosis." (PMID 40895268, 2025). "When SGK1 expressing cells are treated with PI3Kα and PDK1 inhibitors, both AKT and SGK1 are inhibited, inducing tumour regression as a result of FOXO3 activation and mTORC1 inhibition." (PMID 40263319, 2025). "For example, ARSG, CTH, PDK1, and PDK4 are heavily involved in cellular metabolism and oxidative stress regulation, pathways tightly coupled with tumor proliferation and survival under adverse microenvironmental conditions." (PMID 41153607, 2025). "PDK1 inhibitors, such as BX-795 and GSK2334470, have shown promise in preclinical studies across other tumor types." (PMID 40971960, 2025). "Genetic inhibition of PDK1 via RNA interference reduced OSC stemness, glycolysis, and heterotopic tumor formation." (PMID 40730548, 2025). "The results demonstrated that DCA effectively suppressed the tumour growth triggered by overexpression of LINC01419, further indicating that PDK1 is the major downstream effector of LINC0419." (PMID 39625183, 2024). "Pyruvate dehydrogenase kinase 1 (PDK1), a highly expressed enzyme found in mitochondria, plays a vital role in tumor glycolysis and is a potential target for inhibiting glycolysis in cancer cells." (PMID 39771506, 2024). "The pyruvate dehydrogenase kinase (PDK) family, including PDK1, PDK2, PDK3, and PDK4, is closely related to tumour progression." (PMID 38288377, 2024). "These JX06-NPs circulate in the blood, accumulate at tumor sites, and release JX06 to inhibit PDK1, while metformin, administered orally, regulates glucose levels and inhibits mitochondrial complex I to suppress OXPHOS in tumor cells." (PMID 39479443, 2024). "We demonstrated that USP11 overexpression promotes HIF‐1α stabilization and enhances glycolysis through PDK1 and LDHA‐related pathways, eventually leading to tumour cell proliferation and metastasis." (PMID 38229475, 2024). "Consistently, methylated FUBP1, PDK1, and SLC7A11 were also more robustly expressed in tumor tissues." (PMID 39146021, 2024). "When the expression or activity of S1PR1 is inhibited, PDK1 expression is decreased and LATS1/1 is activated, leading to YAP inactivation and tumor cell senescence." (PMID 37828220, 2023). "Exosomes with high expression of circular PDK1 activate c-Myc by regulating the miR-628-3p/BPTF axis and circular PDK1-BIN1 axis, thus, promoting tumor growth, metastasis, and glycolysis." (PMID 37408250, 2023). "The upregulation of pro-apoptotic genes and downregulation of anti-apoptotic genes, mainly MCL1, PDK1 and BCL2, after MET and MET + LPS treatments contributed to the tumor cell death observed." (PMID 36765551, 2023). "Of note, the deregulation of PDK1, TIGAR, and MPC1 was previously strongly correlated with tumor development." (PMID 37508533, 2023). "HIF-1α promotes tumour neoangiogenesis as well as aerobic glycolysis by LDH-A and pyruvate dehydrogenase kinase 1 (PDK1) expression." (PMID 36928373, 2023).
tumor (continued). "Based on the concerted actions of MAPK4-AKT and MAPK4-PDK1 signaling axis in driving MAPK4 tumor-promoting activities, we tested and confirmed that co-blockade of AKT and PDK1 effectively represses MAPK4-induced cancer cell growth." (PMID 37531320, 2023). "These suggest that MAPK4 activates additional signaling cascade(s) beyond PDK1 and AKT for full tumor-promoting activity." (PMID 37531320, 2023). "Constitutive activation of the PI3K/PDK1/AKT pathway and HIF1a pathway under low level of oxygen contribute to increased glycolysis in tumor." (PMID 37183243, 2023). "PDK1 expression regulates the HOXA11 gene and inhibits miRNA518a-3p to promote tumor proliferation and invasion in OSCC." (PMID 37692575, 2023). "β-catenin signaling increases the metastatic capacity of HCC cells through upregulation of pyruvate dehydrogenase kinase isoenzyme-1 (PDK1) to stimulate the Warburg effect and energy delivery to the tumor." (PMID 35454818, 2022). "AR-12 inhibits the phosphorylation of PDK-1 and thus inhibits the activation of the serine/threonine protein kinase Akt (protein kinase B or PKB), tumor cell proliferation, and inducing tumor cell death." (PMID 36435779, 2022). "Silencing of RPN2 also inhibited the expression of HK-2, PDK1, and LDHA in these cells and decreased LDHA level in mouse tumor tissues." (PMID 35156537, 2022). "In a variety of cancer types, PDK1-3 have been proposed to play oncogenic roles, whereas PDK4 has been proposed to play both oncogenic and tumor suppressive functions depending on the tumor type." (PMID 35692804, 2022). "Gene expression data of microdissected stroma from normal breast and TNBC31 showed significant downregulation of PDK2 and low levels of PDK1, PDK3 and PDK4 in the tumour stroma similarly to our CAFs." (PMID 35760868, 2022). "Consistently, the xenograft model confirmed that the forced expression of PDK1 attenuated the suppressive effect of shFOXM1‐treated HONE‐1 cells on the in vivo tumour growth rate, tumour size, and tumour mass." (PMID 35656815, 2022). "It has been reported that aspirin directly downregulates the level of ENO1, PDK1, and PFKFB3 to attenuate glycolysis and tumor progression." (PMID 36319992, 2022). "In this study, we discovered that PDK1 and PDK2 are metabolic checkpoints for tumor progression and CSC features under TGFβ1 modulation within the TME of HNC." (PMID 36474273, 2022). "Two weeks after inoculation, when the tumor volumes reached ~200 mm3, we examined the expressions of HIF-1α and the HIF-1 target genes ADM and PDK1 in the apyrase and shHIF-1α groups to verify the successful establishment of the xenograft models." (PMID 35236823, 2022). "In this study, in addition to PDK1, we further found that PDK2 silencing reduced the stemness features of HNC CSCs, including tumor sphere formation ability, motility, CSC genes, and multidrug-resistant genes (ABC)." (PMID 36474273, 2022). "According to the boxplots analysis, tumor expression of AKT1, AKT2, and PDK1 is higher than the normal." (PMID 35634241, 2022). "Sodium selenite treatment upregulated pro-apoptotic, apoptotic, and tumor suppressor genes such as ATF3, FOSB, GADD45B, DUSP8 and ACHE, and downregulated tumor cell survival genes such as SCD, LRP1, RAB31, SRPX2, PDK1 and CSGALNACT1." (PMID 36059619, 2022). "In consistence with this, the expression of ENO1 and PDK1 were elevated and PRKCB was decreased in matched LUAD tumor tissues compared with normal tissues." (PMID 35504868, 2022). "PDK1 and PDK2 silencing downregulated the tumor sphere formation, motility, CSC genes, and multidrug-resistant genes in HNC CSCs." (PMID 36474273, 2022). "The tumor spheroid-forming capability, motility, CSC genes, and multidrug-resistant genes were downregulated in PDK1 and PDK2 silencing CSCs." (PMID 36474273, 2022).
tumor (continued). "The results showed that this molecule inhibited the activity of PDK1 and LDHA, significantly reduced the production of lactate in tumor cells, increased oxygen consumption, and regulated glucose metabolism." (PMID 35957825, 2022). "Overexpression of Pyruvate dehydrogenase kinase 1 (PDK1) in OC cells impaired IFN-γ secretion in CD8+ T cells by upregulating PD-L1, and an increase in intra-tumor of IFN-γ was observed with DCA (a PDK inhibitor) and anti-PD-L1 antibodies." (PMID 36618371, 2022). "JX06‐NPs entered cancer cells via the blood circulation, and then accumulated in the tumor sites, dissociated to release JX06 to inhibit PDK1." (PMID 35064767, 2022). "PDK1, PDK2, and PDK3 play a role of tumor promoters, while PDK4 plays a different role in tumor aggressiveness depending on the cancer origin." (PMID 36474273, 2022). "PDK1 and PDK2 were knocked down by the lentivirus shRNA system to investigate their role in TGFβ1-promoted tumor progression in vitro." (PMID 36474273, 2022). "In sum, the results of this study demonstrate that TMEM116 via PDK1/AKT/FOXO3A signaling pathway targets TAp63, which is critical in cancer cell motility and tumor metastasis." (PMID 34789718, 2021). "Glucose, hexokinase, PKM2, lactate, PDH, PDK1, SIRT1, and SIRT3, are essential glycolytic and mitochondrial metabolism enzymes controlling tumor progression or regression." (PMID 34771733, 2021). "The ACACA, AR, MAPK, PDK1, PEA15, and SYK showed significant differential expression between normal tissues and tumor tissues (P < 0.0001)." (PMID 33842538, 2021). "XBP-1-HIF-1a complex represents a crucial role in tumor growth and relapse by regulating genes involved in angiogenesis and metabolism such as VEGF, glucose transporter 1 (GLUT1), or pyruvate dehydrogenase kinase 1 (PDK1)." (PMID 34011277, 2021). "Treatment of retinoblastoma cells with OSU increases the tumor suppressive function of miR-363-3p, which regulate PI3CA (phosphatidylinositol 4,5-bisphosphate 3 kinase catalytic subunit α) and PDK1 expression." (PMID 34356673, 2021). "The hidden links between PDK1, PDK2, PDK3, and PDK4 expression and tumor-infiltrating immune cells in GC were assessed by the TIMER database." (PMID 34220962, 2021). "Since both the canonical PI3K/PDK1 pathway and our recently identified MAPK4 pathway can independently regulate AKT activation, the tumor-promoting activities of endogenous MAPK6 are likely to be context dependent." (PMID 34767444, 2021). "The p-PDK1 and p-AKT levels in tumor were tested by immunofluorescence assay using whole cell lysates from NCI-H460 cells treated with baicalin for 48 h." (PMID 34868313, 2021). "MJ-exposed tumor cells showed inhibition of HK 2, LDH A, PDK-1, and HIF-1α expression, which have a pivotal role in maintaining the predominant glycolytic phenotype of tumor cells, crucially required for augmented survival of neoplastic cells." (PMID 33718176, 2021). "Impressively, pyruvate dehydrogenase kinase 1 (PDK1) is a gatekeeper of glycolysis and mitochondrial OXPHOS; its inhibition can reverse the Warburg phenotype of tumor cells." (PMID 34445360, 2021). "In this frame, a phase I clinical trial (NCT01163487) evaluates tumor hypoxia by PET-scan in recurrent head and neck cancers and the possibility to use dichloroacetate (DCA), a drug targeting PDK1, in these tumors." (PMID 34539584, 2021). "Phosphoinositide-dependent kinase-1 (PDK1) is one of the AGC kinase family members, a serine-threonine kinase, and a recently discovered signaling hub for the migration and invasion of tumor cells." (PMID 34868313, 2021). "Knockdown of carbonic anhydrase IX, a factor upregulated under hypoxia conditions, transactivates Let-7d, Let-7c, and Let-7f to suppress LIN28 as well as pyruvate dehydrogenase kinase 1 (PDK1) expression, leading to decreased tumor stemness activity." (PMID 35008539, 2021).
tumor (continued). "Consistent with the in vitro data, inhibition of lncRNA MDFIC-7 expression suppressed the mRNA expression of GLUT1, HK2, PDK1 and LDHA in the xenograft tumor tissues." (PMID 34621682, 2021). "Interestingly, PDK-1 has been also described to promote tumor cell proliferation and migration in non-small cell lung cancer (NSCLC) by enhancing the Warburg effect 7 and previous works demonstrate tight correlation between abnormal cancer cell metabolism and KRAS mutation in several neoplasias." (PMID 33664850, 2021). "Currently, there are several latest research on PDK1 mechanisms involved in JNK/IL-8 signaling and PD-L1 pathway 29, 38, which have little correlation with tumor cell metastasis pathway." (PMID 33403023, 2021). "Either loss-of-function mutations of SPOP or gain-of-function mutations of PDK1 in their binding region all attenuate SPOP recognizing and ubiquitinating PDK1, leading to elevat PDK1 protein abundance, AKT kinase activity and benefit of tumor malignancies." (PMID 34353330, 2021). "In agreement with previous studies, PDK1 silencing lowered glycolysis and promoted OXPHOS in tumor cells grown in vitro; in the context of the tumor microenvironment, the scenario is rather different." (PMID 33562444, 2021). "Presently, the discovery of dual inhibitors simultaneously targeting the PI3K/PDK1/Akt and RAF/MEK/ERK signaling pathways has become a research hotspot in the pursuit of targeted anti-tumor medicine." (PMID 33072436, 2020). "In the case of CP, PDK1 upregulates the expression of EGFR and inhibition of PDK1/EGFR axis can suppress EMT and malignancy of tumor cells." (PMID 32503307, 2020). "Crosstalk between tumor cells and HSCs was mediated by tumor-derived exosomes carrying miR-21 that directly targeted PTEN, leading to activation of PDK1/AKT signaling in HSCs." (PMID 32466591, 2020). "Mechanistically, β-asarone can reduce pyruvate dehydrogenase kinase (PDK) 1, phospho(p)-PDK1, PDK4, hypoxia-inducible factor 1-α (HIF1α), c-myc, STAT5, and p-STAT5 expression, which revealed how β-asarone affects tumor glycolysis." (PMID 32351601, 2020). "In contrast to PDK1–3, data suggest either oncogenic or tumor suppressive function of PDK4, dependent on the metabolic profile of the tumor." (PMID 33384955, 2020). "The transcriptional complex of XBP1 with HIF1α elevates the expression of pyruvate dehydrogenase kinase 1 (PDK1) and glucose transporter 1 (GLUT1) that are the downstream genes of HIF1α, which facilitates tumor development and invasiveness of TNBC." (PMID 31739582, 2019). "In line with the result of in vivo tumor growth, apoptotic HCT116 cells per field were significantly enhanced by silencing PDK1 (P < 0.0001)." (PMID 31506552, 2019). "Pyruvate dehydrogenase kinase-1 (PDK-1), a gatekeeper enzyme, was involved in cancer progression, such as tumor angiogenesis, cell survival, and growth." (PMID 30988063, 2019). "The tumor-promoting role of HOXA11-AS is closely related to its regulation of miR-518a-3p and PDK1 axis." (PMID 31139017, 2019). "In the first tumor transplantation, empty vector with NTC (Ctrl), H19 overexpression with NTC (H19), empty vector plus PDK1 knockdown (shPDK1), and H19 plus shPDK1 MDA-MB-231 cells were subcutaneously transplanted into nude mice (n=5)." (PMID 29106390, 2018). "It has been demonstrated that miR-375 negatively regulates PDK1 and IGF1R and that these effects contribute to the inhibition of tumor proliferation and metastasis." (PMID 27885434, 2017). "SGK1 plays an important role in regulating ion transport as well as cell metabolism and tumor growth, and is activated via PI3K, PDK1 and mTORC2." (PMID 28825630, 2017). "PDK1 plays a pivotal role in modulating PI3K-pathway signaling, and is involved in the regulation of cell metabolism, proliferation, and survival of tumor cells." (PMID 28402933, 2017).
tumor (continued). "One intriguing candidate that has emerged is pyruvate dehydrogenase kinase 1(PDK1), reported to be important in promoting tumor metabolism and growth in variety of cancers including GBM." (PMID 28410193, 2017). "The results showed that TCRP1, p-PDK1 and p-AKT1 were frequently overexpressed in tumor tissue samples compared with normal tissue samples." (PMID 28436990, 2017). "In the present study, we demonstrated that the DAP strongly inhibited cell growth via inhibiting PDK1 in many different AML cell lines, which suggest that PDK1 inhibition has a broad spectrum of anti-tumor effects." (PMID 26593251, 2016). "Based on the results of our study, we inferred that PDK1 protected BCL-2, BCL-xL, and PI3K/Akt/mTOR from degradation and that the persistent stabilization of these proteins made the tumor cells resistant to apoptosis, thus conferring survival advantages." (PMID 26593251, 2016). "In concordance with studies performed in tumor cells before, we demonstrate PGE2 increases normal bronchial epithelial cell proliferation, through increased PDK1 gene expression that is dependent on EP4 and induction of c-Jun." (PMID 26684827, 2015). "We accordingly found PKCη/Rdx-mediated activation of PDK1/PKB signaling to occur in several PV-permissive human tumor cell lines, and this should be relevant to both tumor cell physiology and PV oncoselectivity (compare the left and right panels)." (PMID 25742010, 2015). "Our data supports previous work implicating PDK1 in different cancers and indicating the beneficial effect of its inhibitor DCA in promoting tumor cell apoptosis and inhibiting cancer growth." (PMID 25932951, 2015). "In most tumor cell lines, phosphorylation of PKB at T308 was also observed, suggesting PDK1:S135 phosphorylation mobilizes an intracellular PI3K-independent survival pathway in cancer cells." (PMID 25742010, 2015). "Consistent with that possibility, our studies showed lower PDK-1 (and PDK-2) expression in c4 tumours compared with WT." (PMID 21612605, 2011). "GLUT1, PDK1 and LDHA expression was elevated in CAM tumours relative to tumour cells in vitro." (PMID 41731278, 2026). "AKT3-174aa competes with phosphorylated PDK1 (pyruvate dehydrogenase kinase 1), blocks AKT-thr308 phosphorylation, regulates PI3K/AKT signaling, and inhibits GBM cell proliferation, radiation resistance, and anti-tumor activity in vivo." (PMID 40034125, 2025). "To confirm the correlation between tumor acidosis and metabolic alterations, and indeed their relationship with a malignant phenotype, we evaluated glycolysis markers such as LDH-A and PDK-1, in addition to LAMP2 and CAIX, which are involved in both tumor acidosis and hypoxia." (PMID 40551171, 2025). "The activity of PDHA1 is negatively regulated by pyruvate dehydrogenase kinase 1 (PDK1), which phosphorylates PDHA1 at the Ser232 residue, thereby facilitating a metabolic shift toward glycolysis—a phenomenon frequently observed in tumor cells." (PMID 41465397, 2025). "Specifically, overexpression of glucose transporter 1 (GLUT1) and pyruvate dehydrogenase kinase 1 (PDHK1) in hypoxic conditions promotes anaerobic glycolysis, leading to lactate production that acidifies the TME and facilitates tumor progression, drug resistance, metastasis, and immune escape." (PMID 41438682, 2025). "Additionally, silencing of KLF13 raised the protein levels of SH2B1, IRS1, GLUT1, PDK1, and LDHA in xenograft tumours, and KLF13 overexpression exhibited the reverse actions." (PMID 41410190, 2025). "Whether this holds true in other tumor types remains uncertain, and future studies utilizing PI3K and PDK1 knockout cancer cell lines or animal models are needed to explore this further." (PMID 40789057, 2025). "Moreover, immunohistochemical staining of tumors revealed that PDK1-shRNA tumors lower CD31 expression, a marker used to evaluate tumor angiogenesis." (PMID 38560503, 2024).